BECN1 (beclin 1)
Diseases named in the same sentence as BECN1 in open-access papers (continued):
Sharing a sentence is not in itself a finding about the gene and the disease.
gastric cancer (continued). "Potential miR-409-3p target genes have been previously reported; for example, Beclin-1 in colon cancer, radixin in gastric cancer, and Ras suppressor 1 and stromal antigen 2 in prostate cancer." (PMID 30846940, 2019). "First, Bcl-2 and Beclin-1 antibodies were immunoprecipitated in DSGOST-treated gastric cancer cells." (PMID 29844404, 2018). "D. QRT-PCR analyses of ATG7 and BECN1 gene expression in gastric cancer cell-derived exosomes-treated neutrophils." (PMID 30292233, 2018). "Abnormal expression of Beclin-1 was shown to relate to the occurrence and prognosis of breast cancer, gastric cancer, and lymphoma." (PMID 30107804, 2018). "For example, studies have shown that higher Beclin 1 expression suggested better overall survival in patients with non-Hodgkin's lymphoma, salivary gland carcinoma and gastric cancer." (PMID 28881721, 2017). "For example, fluorouracil up-regulated expression of the protein Beclin-1 triggers autophagic cell death of gastric cancer cells." (PMID 27242439, 2016). "A Chinese study indicates that the level of Beclin 1 is closely correlated to the clinicopathologic characteristics of gastric cancer, including gender, age, and the histological subtype of tumor." (PMID 26910278, 2016). "Upregulated Beclin 1 mRNA and protein is also noted in several gastric cancer cell lines, as compared with that in normal gastric mucosa cell line (GES-1)." (PMID 26910278, 2016). "Beclin-1 expression was observed in 95 and 83% of the colorectal and gastric cancer samples, respectively." (PMID 25789037, 2015). "The expression of BECN1 was evaluated in four human gastric cancer cell lines (AGS, HGC-27, MGC-803 and SGC-7901)." (PMID 26497999, 2015). "Similar protective effects of Beclin 1 have also been reported for gastric cancer, intrahepatic cholangiocellular carcinoma, extranodal natural killer T-cell lymphoma, and stage IIIB colon cancer." (PMID 24675697, 2014). "Furuya found that Beclin 1 can promote the apoptosis induced by the chemotherapeutic drug cis-diamminedichloroplatinum (CDDP) in the MKN28 human gastric cancer cell line by enhancing the caspase 9 activity." (PMID 24675697, 2014). "Beclin 1 promoted the apoptosis induced by the chemotherapeutic drug CDDP in the MKN28 human gastric cancer cell line by enhancing caspase 9 activity." (PMID 24675697, 2014). "Clearly, further studies are required to fully understand the potential function of Beclin 1 in human gastric carcinoma pathogenesis and to identify the signaling pathway involved in the tumorigenesis." (PMID 24527069, 2014). "More recently, we further demonstrated that low expression of Beclin 1 predicted a poor prognosis in gastric cancer." (PMID 24260370, 2013). "In gastric carcinomas, decreased Beclin 1 was correlated with a poor differentiation, lymph nodal and distant metastasis." (PMID 24303007, 2013). "We also revealed Beclin 1 expression is elevated in primary gastric tumors compared with four paired gastric cancer samples adjacent to tumors from the same patients by reverse transcription-PCR and western blotting." (PMID 23029344, 2012). "Beclin-1 expression in gastric cancer cell lines and clinical specimens is also detected using reverse transcription-PCR and Western blotting." (PMID 23029344, 2012). "The possible explaination is that beclin-1 expression in gastric cancers contribute to the induction of autophagic cell death, thereby producing selective pressure to override cell death during development the cancer." (PMID 23029344, 2012). "Further studies are also needed to clarify the mechanism by which autophagy actor Beclin 1 is involved in the development and progression of gastric cancer." (PMID 23029344, 2012). "Beclin 1 is up-regulated at both mRNA and protein levels in six gastric cancer cell lines compared with those in normal gastric mucosa cell line (GES-1)." (PMID 23029344, 2012).
gastric cancer (continued). "The current study has, for the first time, showed Beclin 1 is up-regulated at both mRNA and protein levels in six gastric cancer cell lines compared with those in normal gastric epithelial cells GES-1." (PMID 23029344, 2012). "The correlation of Beclin 1 expression to clinicopathologic features and survival of gastric cancer was studied." (PMID 23029344, 2012). "On the other hand, Beclin 1 expression is reportedly increased in colorectal and gastric cancer cells and these discrepant results indicate that Beclin 1 probably has different functions in different tissues." (PMID 22928777, 2012). "Patients with Beclin 1 low expression gastric cancer showed significantly shorter 5-year overall survival rates (OS, p = .011) and disease free survival (DFS, p = .010) than those with Beclin 1 high expression ones." (PMID 23029344, 2012). "The purpose of the present study is to investigate the expression of beclin 1 in gastric cancer cells, tissues and its relationship with prognosis." (PMID 23029344, 2012). "We found that Beclin 1 mRNA and protein expression level up-regulated in all six gastric cancer cell lines compared with normal gastric epithelial cells GES-1." (PMID 23029344, 2012). "The present study investigated Beclin 1 expression in gastric cancer cells, tissues and its clinicopathologic significance in patients with lymph node-positive gastric cancer." (PMID 23029344, 2012). "Previous studies demonstrated that over-expression of beclin 1 induced apoptosis via activation of caspase-9 in gastric cancer cells, while partial silencing of beclin 1 aggravated apoptosis in hepatic cancer cells." (PMID 20230646, 2010). "Similarly, a decreased expression of Beclin 1 in gastric cancer correlates with lymph node metastasis, TNM staging, dedifferentiation, and adverse prognosis." (PMID 39664581, 2024). "Interestingly, C-2 induces autophagy and enhances p62 expression in gastric cancer cells by activating the JNK/ERK/Beclin 1 pathway." (PMID 39664581, 2024). "In recent years, a relationship between gastric cancer and BECN1 expression has been reported." (PMID 37740192, 2023). "Recent studies demonstrated that Beclin-1 is triggered by miR-140-3p in gastric cancer." (PMID 35884904, 2022). "The high expression of Beclin-1 predicts a worse prognosis of gastric cancer." (PMID 35719323, 2022). "Another report suggested that treated with CQ or specific small interfering RNA (siRNA) targeting Atg5 or Beclin 1 could promote quercetin-induced cell apoptosis against gastric cancer." (PMID 36611961, 2022). "In order to explore whether SS triggered autophagy in gastric cancer cells, we first detected the expression of autophagy-associated proteins, such as LC3, Beclin-1 and p62." (PMID 33708631, 2021). "Our findings support the opinion that Becn-1-mediated gastric cancer might originate from local stem cells with genetic alteration, but not the differentiated cells." (PMID 33425768, 2020). "We conducted a GSEA to analyze Becn1-related signal pathways in gastric cancer." (PMID 33425768, 2020). "The prognostic significance of Becn1 mRNA in gastric cancer by Kaplan–Meier plotter." (PMID 33425768, 2020). "Taken together, Beclin 1 might be considered as a potential marker for the prognosis of the gastric cancer patients at either mRNA or protein level." (PMID 33425768, 2020). "In agreement with our observations, a meta-analysis using 23 independent studies recently concluded that a high BECN1 expression was a favorable predictive factor for overall survival (OS) in BC, gastric cancers and lymphomas, whereas high levels of LC3B were inversely correlated with OS in BC." (PMID 33488952, 2020). "Becn1-enriched signal pathway in gastric cancer according to the KEGG analysis." (PMID 33425768, 2020). "Moreover, Beclin 1 overexpression suppressed tumor growth of gastric cancer cells in nude mice (P<0.05)." (PMID 33425768, 2020).
gastric cancer (continued). "These suggested that Beclin 1 might be considered as a potential marker of gastric carcinogenesis, aggressiveness and prognostic prediction, and as a target of gene therapy in gastric cancer." (PMID 33425768, 2020). "Similarly, mulberry anthocyanins induced autophagy, increasing the LC3 II/LC3 I ratio and the expression of Beclin 1 in human gastric cancer cells (SGC-7901)." (PMID 32927836, 2020). "Thus, the expression levels of SIRT1 and/or Beclin-1 are potential prognostic indicators for gastric cancer and are potential therapeutic targets for the disease." (PMID 31492861, 2019). "Beclin 1 is identified as an independent prognostic factor for gastric cancer." (PMID 26910278, 2016). "In addition, some of the autophagy-related proteins, such as Beclin 1, microtubule-associated protein 1 light chain 3 (MAP1-LC3), and p62/sequestosome 1 (SQSTM1) have certain prognostic values for gastric cancer." (PMID 26910278, 2016). "The alternative explanation for this may be that beclin-1 expression in gastric cancers limits chromosomal instability and decreases the frequency of additional mutation." (PMID 23029344, 2012). "In addition, overexpression of Beclin 1 has been shown to enhance the sensitivity of cervix and gastric cancer cells to chemotherapeutic drugs." (PMID 23270461, 2012). "The results strongly suggest that Beclin 1 has a potential role in tumorigenesis of gastric cancer." (PMID 23029344, 2012). "The expression of Beclin 1 and its prognostic role in gastric cancer is largely unexplored." (PMID 23029344, 2012). "Our findings strongly suggest that Beclin 1 has a potential role in tumorigenesis of gastric cancer and could be a promising biomarker for predicting the prognosis of patients with lymph node-positive gastric cancer." (PMID 23029344, 2012). "Inhibiting autophagy using a well-known antimalarial drug, chloroquine and using siRNA against beclin-1 resulted in a reduction in viability of gastric cancer cell lines in the presence of vorinostat, suggesting autophagy is activated as a protective survival response after vorinostat treatment." (PMID 21931799, 2011). "Piceatannol’s inhibition of Beclin-1 may hinder the advancement of gastric cancer." (PMID 39650649, 2024). "Consequently, Bax overexpression and Bcl-2 underexpression in gastric cancer cells may account for the inductive effect of Beclin 1 on apoptosis via mitochondrial pathway." (PMID 33425768, 2020). "Trastuzumab or pertuzumab in combination with Les-4367 decreased Beclin-1, LC3A, and LC3B concentrations in AGS gastric cancer cells." (PMID 37047765, 2023). "However, BECN1 could repress tumorigenesis in synovial sarcoma and gastric cancer." (PMID 35012553, 2022). "NUCKS silencing increases autophagy through the mTOR- Beclin-1 pathway, implicating NUCKS as potential therapeutic target in gastric cancer." (PMID 35884904, 2022). "However, the deficiency of Beclin‐1 in SGC‐7901 completely blocked BIX combined Cis induced pyroptosis as well as apoptosis, which suggested that BIX enhances the sensitivity of anticancer therapeutics in gastric cancer through the activation of autophagic flux." (PMID 32437063, 2020). "As a result, 17/32 (53.1%) advanced tubular gastric cancers exhibited immunohistochemical evidence of at least two autophagy-related proteins (LC3 A/B and Beclin 1)." (PMID 30893939, 2019). "Gastric cancer tissue-derived exosomes also induced higher ATG7 and BECN1 expression and NF-κB activation in neutrophils than non-cancerous tissue-derived exosomes." (PMID 30292233, 2018).
gastric cancer (continued). "Recombinant HMGB1-treated neutrophils promoted the migration of gastric cancer cells and increased the expression of ATG7 and BECN1 genes in neutrophils." (PMID 30292233, 2018). "We monitored the accumulation of LC3B, Beclin-1, and ATG5 and the downregulation of p62 levels in gastric cancer cells." (PMID 29844404, 2018). "In gastric cancer, high CHAC2 expression was correlated with XBP-1s, active caspase-3 or Beclin 1 high expression with a correlation coefficient of 0.305 (P=0.002), 0.607 (P<0.001) and 0.591 (P<0.001), respectively." (PMID 28837156, 2017). "The role of autophagy in KSP-inhibited gastric cancer growth was further confirmed by assaying the protein levels of LC3-II and beclin-1 in tumor tissue." (PMID 29221112, 2017). "KSP significantly increased the levels of LC3-II and beclin-1 in tumor tissues, which was ablated by 3-MA, suggesting that KSP via induction of autophagy inhibits gastric cancer growth in vivo." (PMID 29221112, 2017). "Hence, Beclin 1-dependent autophagy might be required for tumor angiogenesis of gastric cancer." (PMID 26910278, 2016). "Here, BTG3 overexpression was found to in vivo and vitro induce the autophagy of gastric cancer cells with Beclin 1 overexpression, indicating that BTG3-mediated autophagy was dependent on beclin-1 expression." (PMID 25904053, 2015). "Conversely, colorectal, gastric cancer and pancreatic ductal adenocarcinoma cells have shown increased expression, whereas, in adjacent noncancerous tissues, little to no Beclin-1 expression was observed, implying tissue-specific functions for Beclin-1." (PMID 38596136, 2024). "In gastric cancer SNU-1 cells, Naringin similarly activated autophagy in gastric cancer SNU-1 cells by inhibiting the PI3K/AKT signaling pathway, upregulating the expression of LC3B and Beclin-1 and downregulating the expression of p62." (PMID 37663256, 2023). "Beclin 1 down-regulated the expression of VEGF, E-cadherin, Bcl-2, but up-regulated the expression of LC-3B, NF-κB, PI3K, Akt1/2/3 and MDR in xenograft tumor of gastric cancer cells." (PMID 33425768, 2020). "The treatment of HGC-27 gastric cancer cells with TET resulted in a significant increase in the expression of proteins engaged during autophagy initiation and autophagosome formation, such as LC3-II and Beclin-1." (PMID 33167519, 2020). "Therefore, the inhibitory of Beclin 1 on migration and invasion was dependent on MET in gastric cancer cells." (PMID 33425768, 2020). "However, naringin (2 mM) was also able to induce autophagy, as shown by the formation of cytoplasmic vacuoles and autophagosomes, through the activation of Beclin 1 and LC3 II in human AGS gastric cancer cells." (PMID 32927836, 2020). "To confirm whether DSGOST can interfere with the interaction between Beclin-1 and Bcl-2, we examined the co-immunoprecipitation of Beclin-1 and Bcl-2 in DSGOST-mediated gastric cancer cells." (PMID 29844404, 2018). "In addition, HMGB1 antagonist reversed gastric cancer tissue-derived exosomes-induced increases of ATG7 and BECN1 expression in neutrophils." (PMID 30292233, 2018). "Increased Beclin 1 and LC3-I/II conversion was detected in human gastric cancer tissues." (PMID 26910278, 2016). "Autophagy markers such as LC3B and Atg5, and KLK6 which is gastric cancer biomarker, but not beclin-1, showed increased expression over 16 h after AF treatment." (PMID 27863404, 2016). "Beclin 1 expression is negatively correlated with the poor tumor differentiation, tumor metastasis, advanced tumor-node-metastasis (TNM) stage, tumor recurrence as well as shorter survival in gastric cancer patients." (PMID 26910278, 2016). "The interaction of etoposide with pertuzumab or trastuzumab induced programmed cell death via extrinsic and intrinsic apoptotic pathways in AGS gastric cancer cells but did not affect autophagy, where a decrease in Beclin-1, LC3A, and LC3B was observed compared with the untreated control." (PMID 37047765, 2023).
gastric cancer (continued). "Notably, the expression level of Beclin-1 in the LBP group was similar to that in normal AGS cells without special treatment, suggesting that the high expression of Beclin-1 in gastric cancer cells does not seem to be beneficial for antitumor therapy." (PMID 35719323, 2022). "The interaction of etoposide with pertuzumab or trastuzumab induced programmed cell death via extrinsic and intrinsic apoptotic pathways in AGS gastric cancer cells, but did not affect autophagy, where a decrease of Beclin-1, LC3A and LC3B was observed in comparison with the untreated control." (PMID 34437575, 2021). "Becn1 overexpression was found to markedly attenuate the ability of gastric cancer cells to migrate and invade possibly due to VEGF hypoexpression because VEGF may promote mobility and proliferation of gastric cancer cells." (PMID 33425768, 2020). "Furthermore, we observed non-canonical Beclin-1-independent autophagy and subsequent caspase-dependent apoptosis that ultimately leads to the death of gastric cancer cells." (PMID 30096805, 2018). "However, another Korean study shows that the Beclin 1 level is not correlated with the clinicopathologic properties of patients with gastric cancer, including metastasis, invasion, and stage." (PMID 26910278, 2016). "And negative expression of BECN1 could be an independent prognostic marker for predicting shorter overall survival and progression-free survival in gastric cancer patients." (PMID 26497999, 2015). "Moreover, BECN1 expression was negatively correlated with expression of HIF-1α (P = 0.042) and GLUT-1 (P = 0.046), and positively correlated with E-cadherin expression (P = 0.006) in gastric cancer tissues." (PMID 26497999, 2015). "We observed p-p38 overexpression in Becn1-ovexpressing or silencing gastric cancer cells, but both p-PI3K and p-Akt hyperexpression was seen in Becn1-ovexpressing, but not Becn1-knockdown cells, suggesting that PI3K/Akt signal pathway might be involved in the effects of Beclin 1, but not p38." (PMID 33425768, 2020).